ABCG2 (ATP binding cassette subfamily G member 2 (JR blood group))
Diseases named in the same sentence as ABCG2 in open-access papers (continued):
Sharing a sentence is not in itself a finding about the gene and the disease.
tumor (continued). "Thus, the poor prognosis in patients with marker CD44+ABCG2-ALCAM- or CD44-ABCG2+ALCAM- might be related to the more active biological processes in LCSCs and greater tumor dedifferentiation." (PMID 36613925, 2022). "Above results suggest that A011 could induce apoptosis and down-regulate ABCG2 protein expression in MCF-/ADR tumor cells in vivo, without significant toxicity to liver and kidney tissues." (PMID 36120340, 2022). "Based on these results, the authors concluded that in OS, CCN2 increases ABCG2 expression and promotes drug resistance through the downregulation of miRNA-519d and that CCN2 inhibition might be considered as a new therapeutic option for this tumor." (PMID 34572110, 2021). "Our findings in this study corroborated the tumor-suppressive roles of miR-142-3p, in that transfection of CRC cells with miR-142-3p mimic molecules resulted in decreased expressions of LGR5, β-catenin, mTOR, and IL-6 as well as reduced SPs, as a surrogate of reduced ABCG2 expression." (PMID 32560222, 2020). "Similarly, co-delivery of wedelolatone (Wdl) and paclitaxel incorporated within PLGA NPs downregulated the ABCG2 and SOX-2 expression, sensitising tumour cells to paclitaxel treatment, and reducing the overall percentage of ALDH+ CSCs in vitro and in solid tumours." (PMID 31835751, 2019). "In our study, micro-vessels could not be isolated; therefore, the measured ABCB1 and ABCG2 levels represented membrane-bound transporters of all cell types present in the sample (e.g., micro-vessels, glia cells, neurons and tumor cells)." (PMID 31832814, 2019). "Almost no tumor was formed by the simultaneously downregulated ABCG2 and OCT-4 cells." (PMID 28212529, 2017). "Thus, ABCG2 was highly expressed in tumor tissues compared with the adjacent non-cancerous tissues (P < 0.01)." (PMID 28029654, 2017). "We further performed IHC staining against ST6Ga1, GLUT5, and ABCG2, and divided samples into high and negative/low (-/low) expression groups based on the staining intensity and amount of positively stained areas in the epithelial structure of tumor lesions." (PMID 28032597, 2017). "While SOX2 may be acting to protect tumor cells through antiapoptotic signaling or quiescent-like phenotypes, SOX2 may also be promoting drug resistance through various ATP-binding cassette (ABC) transporters, including ABCG2, ABCC3, and ABCC6." (PMID 28388544, 2017). "Furthermore, immunohistochemistry analysis revealed that PCNA, ABCG2, and OCT4 were positive in the tumor tissues caused by K3-SP but negative in the tumor tissues caused by K3-NSP." (PMID 28465472, 2017). "Importantly, despite regulating these key characteristics of stem-like tumor cells, ABCG2 activity did not affect radiation resistance or tumorigenicity in vivo." (PMID 27456282, 2016). "Importantly however, even when enhancing these central features of tumor stemness, ABCG2 activity did not increase radiation resistance or tumorigenicity of such murine or human GBM cells." (PMID 27456282, 2016). "Tumorigenic PC3 cells may be enriched by the ALDH+ phenotype but not ABCG2 whereas only the CD44+α2β1+ phenotype can enrich tumor-initiating cells in the LAPC4 model." (PMID 26246472, 2015). "An important observation from the work by Traxl and colleagues, which may have important clinical significance for the use of [11C]erlotinib, is the fact that the distribution of [11C]erlotinib in peripheral, and probably tumor tissues, was affected by ABCB1/ABCG2." (PMID 26690113, 2015). "Since our results indicated that BCRP/ABCG2-mediated drug efflux reduced the anti-tumor activity of sorafenib in HCC cells, we next addressed whether combination with BCRP/ABCG2 inhibitors is a potential strategy to increase the sensitivity of HCC cells to sorafenib." (PMID 24391798, 2013). "A better understanding of ABCG2 regulation by the tumor microenvironment may help design novel strategies to improve treatment outcome." (PMID 22778999, 2012).
tumor (continued). "This low percentage of SP in tumour cells could be because the expression of ABCG2 protein was not maintained from NA16 to the tumour stage because of the diversification in there expression pattern." (PMID 21122158, 2010). "Molecular modeling indicated strong binding affinities of ER to both ABCB1 and ABCG2 proteins, supporting the hypothesis that Erastin interacts directly with ABC transporters, modulating their activity and thereby enhancing chemotherapeutic drug retention in resistant tumor cells." (PMID 39859349, 2025). "Moreover, exosomes contribute to tumor chemotherapy resistance by facilitating the activity of efflux pump transporters such as P-glycoprotein(P-gp), multidrug resistance protein-1 (MRP-1), ATP-binding cassette transporter A3 (ABCA-3), and ATP-binding cassette transporter G2 (ABCG-2)." (PMID 40309240, 2025). "Our findings suggest that TSD+ CSCs, a subpopulation of EpCAM+/ABCG2+ CSCs, might engage in a form of self-sacrifice to protect the R-CSC, a pool of dormant CSC population capable of reawakening upon encountering future cisplatin-induced stress and resuming tumor growth." (PMID 39963656, 2024). "Therefore, ABCG2 may not be an ideal marker for tumor stem cell sorting, but it is an important marker to identify tumor drug resistance." (PMID 39668824, 2024). "The average expression level of the ABCA2 (p = 0.000), ABCB1 (p = 0.000), and ABCG2 (p = 0.001) genes was statistically significantly higher in patients with diagnosed tumor cell infiltration into fat tissue compared to patients without tumor cells in the fat tissue." (PMID 36674773, 2023). "Moreover, whether changes in ABCG2 expression occur between primary tumor and metastases is not fully known." (PMID 32708825, 2020). "In contrast, our recent exploratory study of ABCG2 mRNA expression in 580 patients with stage III primary CRC (subgroup from the randomized PETACC-3 study) indicated that high ABCG2 tumor tissue mRNA expression might be predictive for lack of efficacy of irinotecan." (PMID 28880238, 2017). "Finally, in PIGPCs with ABCG2 or empty control expression under Dox control, the addition of Dox significantly reduced sphere formation in Tet-ABCG2 SP but not Tet-ABCG2 MP, Tet-Empty SP or Tet-Empty MP cells, again suggesting an ABCG2-specific regulation of tumor cell self-renewal." (PMID 27456282, 2016). "Nevertheless, the regulatory network on ABCG2 has not been fully clarified, given the role of the MAPK signaling pathway in tumor growth and drug resistance." (PMID 41541684, 2026). "Our findings indicate that the major ABC transporters ABCG2, ABCC1, and ABCB1 are not modulated by agmatine treatment in colon cancer cells and do not mediate resistance to agmatine in Caco-2 tumor cells." (PMID 41557172, 2026). "There were no significant changes in expression between the tumor and control tissues in the ABCB4, ABCA13, ABCC2, ABCC3, and ABCG2 genes." (PMID 36674773, 2023). "Again, transfection with miR-637 inhibitor failed to increase the number of tumor spheres and up-regulate the expression of stemness-related genes (SOX4, SOX9, Nanog, CD44 and ABCG2) after stable knockdown of WASH in KYSE70 cells." (PMID 36329557, 2022). "In OSCC, SP cells were found to express higher levels of ABCG2 than non-SP cells, suggesting that high expression of BCRP in SP cells promotes the progression of drug resistance, proliferation and tumor invasion." (PMID 35204785, 2022). "This treatment significantly reduced the expression of ABCG2 in HT29 cells by increasing the concentration of CPT, inducing an in vivo growth inhibition (90%) of the tumor without recurrence." (PMID 33923200, 2021). "Expressions of ABCG2, ALDH1A1, and ALDH3A1 were negatively related with immune infiltration level in HCC, and showed no relation with tumor purity." (PMID 32184801, 2020).
tumor (continued). "In line with expression of ABCG2 and OCT4, expression of TBX21 was significantly higher in SP cells (P < 0.0001) and tumor spheres (P < 0.0001) compared with non-SP cells or nonspheres." (PMID 29615105, 2018). "There was no change in size of the tumor between SW480 and SW480/ABCG2 injected mice immediately after PDT." (PMID 26149077, 2015). "As for ABCG2, CXCR6+ cells were also undetectable in tumor xenografts by flow cytometry (data not shown)." (PMID 21203549, 2010). "The results showed that not every tumor tissue expressed CD44, CD24 or ABCG2, but the expression of EpCAM could be detected." (PMID 36132125, 2022). "In this context, tumours with highly upregulated ABCB1 expression may be unlikely to respond to either THZ1 or ICEC0942, whereas tumours with high ABCG2 expression may derive benefit from ICEC0942 treatment." (PMID 31530935, 2020). "Previous studies showed tumor cell lines overexpressing MDR1, multidrug resistance protein 1 (MRP1) and ABCG2 were not cross-resistant to ART,39–41 indicating that ART is not a substrate for MDR1, MRP1 and ABCG2." (PMID 35547242, 2019). "Likewise, ABCG2 and ABCB1 expression levels in the original tumours did not explain the multidrug resistance observed in the derived cultures." (PMID 28877221, 2017). "Local esterase activity within the tumor cleaves off the bulky PEG moiety and releases SN38, which passes the plasma membrane and inhibits nuclear topoisomerase I. ABCG2 is apparently not a sufficiently effective defense mechanism against sustained SN38 delivery by EZN-2208." (PMID 23028879, 2012). "However, it does not exert an additive anti-tumor effect with cytotoxic drugs such as doxorubicin and mitoxantrone at the concentrations and times studied, despite downregulating the gene expression of MDR1 and ABCG2." (PMID 38672378, 2024). "Subsequently, in several non-P-gp MDR tumour cell lines high levels of other members of the ATP-binding cassette (ABC) transporter superfamily were identified: the Multidrug Resistance Protein 1 (MRP1; ABCC1; reviewed in Cole and Deeley (1998) and the Breast Cancer Resistance Protein (BCRP; ABCG2)." (PMID 12085191, 2002). "Notably, unspecific low-to-moderate expression of ABCB6 (median score 8, range: 8–9), ABCG2 (median score 3, range: 1–4), FECH (median score 4, range: 1–8) and CPOX (median score: 1, range: 0–1) was also found in all nine fluorescent cortex samples lacking tumor invasion." (PMID 36612300, 2023).
infection (78 papers, 2008 to 2026). The state of being infected such as from the introduction of a foreign agent such as serum, vaccine, antigenic substance or organism. "In this study, a shRNA-encoding retrovirus with high infection efficiency was used to stably express a hairpin structure targeting the ABC domain of BCRP/ABCG2, and cell and animal experiments were conducted." (PMID 25076217, 2014). "Differences in placental Abcb1 (P-gp encoding gene in the human) and Abcg2 (BCRP) mRNA expression-associated with infection and inflammation have been previously reported in human placenta." (PMID 23762418, 2013). "RT-qPCR analyses confirmed that T3 treatment significantly stimulated the expression of ABCB1 and ABCG2 mRNA in both the control-infection and TRα1 GOF conditions at all time points." (PMID 38693105, 2024). "The same analytic method revealed ascites (p = 0.000), CP score (p = 0.001), infection during treatment (p < 0.001), and ATP-binding cassette subfamily G member 2 (ABCG2)-rs2231142 genotype (p = 0.003) as independent predictors in cohort-2 patients." (PMID 35566676, 2022). "In this study, multiple RNA hairpins were designed to target the ABC domain of BCRP/ABCG2, and stable shRNA-expressing recombinant retroviruses with high infection rates were constructed." (PMID 25076217, 2014). "It was observed that the more intense the infection, the higher the level of ABCG2 expression." (PMID 26578453, 2016). "The more intense the infection, the higher the level of ABCG2 expression was observed." (PMID 26578453, 2016). "Western blot results revealed that the expression of SIRT4, and a panel of stem cell-related molecules including ABCG2, BMI1, and NANOG was significantly suppressed in Hep-12 cells following infection with lentiviruses harboring SIRT4 shRNAs." (PMID 40384857, 2025). "Together, these data suggest that infection and inflammation can modulate the expression of ABCG2 and BCRP in placental trophoblasts." (PMID 31561453, 2019). "ABCG2 and BCRP are time-depedently expressed in the placenta, and are modulated by infection and inflammation in a gestational-age dependent manner." (PMID 29402780, 2018). "Both ABCG2 and FKBP5 were also identified as DEG in the recent transcriptional comparison of uninfected quarters from healthy and mastitic animals, suggesting that their differential expression was due to the infection of neighbouring quarters with E. coli." (PMID 23324411, 2013). "However, there appears to be some tissue-specificity in the impact of infection on BCRP, as we previously showed that ssRNA (and LPS) treatment of placental extravillous trophoblast cells (HTR-8/SVneo) decreased BCRP and ABCG2 mRNA expression, though activity was not measured." (PMID 36721242, 2023).
adenocarcinoma (12 papers, 2016 to 2026). A common cancer characterized by the presence of malignant glandular cells. "We found an experimental support for the hypothesis that ABCG2 plays a role in preventing protein aggregation caused by CSC in adenocarcinoma cell line A549, most likely via efflux of toxic compounds and/or smoke induced radicals." (PMID 38442133, 2024). "Elevated ABCG2 levels are responsible for decreasing the intracellular accumulation and thus the efficiency of another anthraquinone derivate—hypericin—as was shown by the decreased efficacy of the hypericin-mediated treatment of adenocarcinoma cells." (PMID 33916015, 2021). "Our present findings indicate significantly lower promoter methylation levels in both colon and rectum adenocarcinomas in comparison to noncancerous tissues; however, only a weak negative correlation was found between ABCG2 expression and methylation level." (PMID 37445716, 2023).
bacterial infection (8 papers, 2014 to 2021). "Bacterial infection has the potential to change yolk sac barrier function by affecting Bcrp and Abcg2 expression in a gestational-age dependent-manner." (PMID 32916274, 2020). "In conclusion, we have demonstrated for the first time, that the yolk sac protective barrier modulated by Bcrp/Abcg2 is disrupted by bacterial infection in a gestational-age dependent manner." (PMID 32916274, 2020). "Lipopolysaccharide (LPS; modelling bacterial infection) decreased ABCG2 and BCRP expression in first trimester human placental explants (but not in third trimester explants)." (PMID 31561453, 2019). "To investigate how bacterial infection impacts placental efflux transport potential, we investigated the expression of the of Abca1, Abcb1a, Abcb1b, Abcb4, Abcc2, Abcc5, Abcf2, Abcg1 and Abcg2 mRNAs in the mouse placenta at GD15.5 or GD18.5 following LPS challenge (4 h)." (PMID 34394055, 2021). "In the present study, LPS treatment, which models bacterial infection via TLR-4 activation, decreased ABCG2 mRNA and BCRP protein expression in HTR-8/SVneo cells." (PMID 31561453, 2019). "For example, ABCG2 gene is responsible for the active secretion of clinically and toxicologically relevant substrates into the milk and soluble CD14 in colostrum and milk acts as a sentinel molecule and an immune modulator, which provide innate responses against bacterial infections in the calf." (PMID 27441113, 2016).
myopathy (8 papers, 2018 to 2026). A disease of the muscle in which the muscle fibers do not function properly. "ABCG2 rs2231142 (c.421C>A) results in the reduced activity of the efflux transporter and thus increased statin plasma levels and an increased risk of statin-induced myopathy." (PMID 37623436, 2023). "Variants in SLCO1B1, ABCG2, and CYP2C9 were combined into a functional PGx burden score, and their associations with statin regimen modification, intolerance, myopathy, liver injury, adherence, and composite adverse events were evaluated." (PMID 41901359, 2026). "SNPs related to myopathy, like the SLCO1B1, ABCB1, and ABCG2 gene polymorphisms, could be taken into account when considering combined treatment with statins." (PMID 30050433, 2018). "Other SNPs associated with myopathy are the polymorphisms in the ABCB1 and ABCG2 genes." (PMID 30050433, 2018).
breast (7 papers, 2011 to 2023). "The use of PBA in IR injury affected the levels of the ABC transporter genes (Abcc2, Abcc5, and Abcg2), significantly suppressed inflammation and oxidative stress, reduced ER stress, and thus significantly mitigated liver IR injury." (PMID 38168520, 2023).
kidney disease (7 papers, 2011 to 2025). "The Polycystin-2 (Polycystic kidney disease 2 gene, PKD2) is involved in enamel–dentine signalling and tissue organisation, while ABCG2 (ATP-binding cassette sub-family G member 2) may help eliminate harmful substances during mineralisation." (PMID 40869999, 2025).
brain diseases (6 papers, 2012 to 2025). "Thus, although P-gp appears to often be the dominant ABC transporter at the blood-brain barrier, these data suggest that dual P-gp/ABCG2 inhibitors may have even greater therapeutic promise for brain diseases." (PMID 34993424, 2021).
cardiovascular disease (6 papers, 2011 to 2024). "We investigated the association between ABCG2 rs2231142 genetic variants and the Framingham Risk Score for Cardiovascular Disease (FRS-CVD) in a Taiwanese population." (PMID 39315221, 2024). "Previous studies evidenced that Nrf-2 expression also influences the expression of ABCG2, a transmembrane transporter protein responsible of GSH transport and associated with redox regulation in some pathological conditions such as Alzheimer’s and cardiovascular diseases." (PMID 32429083, 2020).
neurological disorders (6 papers, 2016 to 2023). "Finally, a diverse array of multi-substrate efflux pumps including ABCB1/MDR1 (p-glycoprotein), ABCC1 (MRP1) and BCRP/ABCG2, actively transport unwanted substances back to the luminal side, including most drugs of potential value for neurological disorders." (PMID 34452156, 2021). "The PET protocol employed in the present study allowed for the first time measuring the transport activity of ABCG2 at the human BBB and might also be applicable to investigate cerebral ABCG2 function in other settings, such as in different neurological diseases." (PMID 26940368, 2016).
hematological malignancies (5 papers, 2015 to 2022). "ABCG2 expression has been reported to be significantly increased in some solid tumors and hematologic malignancies, correlated to poor clinical outcomes." (PMID 26515463, 2015).
metabolic disorders (4 papers, 2020 to 2026). "In conclusion, C. spicatus protects rats from HUA via improving renal function, regulating UA transporters (URAT1, GLUT9, and ABCG2) and remodeling metabolic disorders." (PMID 38965392, 2024).
genetic disorder (3 papers, 2014 to 2017). "Importantly, the proposed mechanism can answer key open questions about ABCG2 and thus may help to revamp efforts to therapeutically modulate ABCG2 in case of malignant or genetic diseases." (PMID 29061978, 2017).